RNU6-1304P (RNA, U6 small nuclear 1304, pseudogene)
Gene: Small nuclear RNA gene on chromosome 1 (225,741,275 to 225,741,380, forward strand). Ensembl gene ENSG00000223306.
Homologues: Orthologues: macaque U6 (81% identical), guinea pig U6 (70% identical), rat LOC120094417 (67% identical), pig U6 (65% identical), chimpanzee U6 (52% identical). Paralogues in human: RNU6-333P (78% identical), RNU6-1084P (77% identical), RNU6-20P (77% identical), RNU6-331P (77% identical), RNU6-1235P (76% identical), RNU6-144P (76% identical), RNU6-14P (76% identical), RNU6-16P (76% identical), RNU6-247P (76% identical), RNU6-25P (76% identical), RNU6-38P (76% identical), RNU6-429P (76% identical), and 1289 more.